FAM32A (family with sequence similarity 32 member A)
Description:
Isoform 1, but not isoform 2 or isoform 3, may induce G2 arrest and apoptosis. May also increase cell sensitivity to apoptotic stimuli.
Synonyms: OTAG-12; OTAG12; DKFZP586O0120
Tractability: Small molecule: a structure with a bound ligand is known. PROTAC: ubiquitination databases record sites on it.
Gene: Protein-coding gene on chromosome 19 (16,185,380 to 16,192,048, forward strand). Ensembl gene ENSG00000105058.
Subcellular location: Nucleus (Isoform 1); Nucleus (Isoform 2)
Subcellular location (Human Protein Atlas): Nucleoli; Nucleoplasm
Pathways (Reactome):
Metabolism of RNA: mRNA Splicing - Major Pathway
Gene Ontology:
Molecular function: protein binding; RNA binding
Biological process: mRNA splicing, via spliceosome
Cellular component: nucleolus; nucleoplasm; spliceosomal complex; U2-type catalytic step 1 spliceosome; U2-type catalytic step 2 spliceosome; nucleus
Genetic constraint (gnomAD): Loss-of-function variants: 9 observed, 14.05 expected, observed/expected ratio (o/e) 0.64, 90% interval 0.38 to 1.12. The upper end of that interval is the gene's LOEUF score, 1.12, which puts it in group 4 of 6, group 1 being the genes least tolerant of losing a copy. Missense variants: 113 observed, 126.05 expected, observed/expected ratio (o/e) 0.9, 90% interval 0.77 to 1.05. Synonymous variants: 64 observed, 50.05 expected, observed/expected ratio (o/e) 1.28, 90% interval 1.04 to 1.57.
Homologues: Orthologues: chimpanzee FAM32A (100% identical), macaque FAM32A (100% identical), pig FAM32A (98% identical), rat Fam32a (98% identical), guinea pig FAM32A (97% identical), mouse Fam32a (97% identical), rabbit FAM32A (97% identical), rat Fam32al1 (90% identical), tropical clawed frog fam32a (73% identical), zebrafish fam32a (68% identical), Drosophila melanogaster CG15432 (50% identical), Caenorhabditis elegans K01G5.8 (38% identical).
Diseases named in the same sentence as FAM32A in open-access papers:
FAM32A is named in the same sentence as 3 diseases in open-access papers, as found by Europe PMC text mining. Sharing a sentence is not in itself a finding about the gene and the disease.
FAM32A shares sentences with these, for which no sentence is quoted: autoimmune disease (1 paper); metastatic tumor (1); serous ovarian cancer (1).